SEPTIN4 (septin 4)
Description:
Filament-forming cytoskeletal GTPase (Probable). Pro-apoptotic protein involved in LGR5-positive intestinal stem cell and Paneth cell expansion in the intestines, via its interaction with XIAP (By similarity). May also play a role in the regulation of cell fate in the intestine (By similarity). Positive regulator of apoptosis involved in hematopoietic stem cell homeostasis; via its interaction with XIAP (By similarity). Negative regulator of repair and hair follicle regeneration in response to injury, due to inhibition of hair follicle stem cell proliferation, potentially via its interaction with XIAP (By similarity). Plays an important role in male fertility and sperm motility. During spermiogenesis, essential for the establishment of the annulus (a fibrous ring structure connecting the midpiece and the principal piece of the sperm flagellum) which is a requisite for the structural and mechanical integrity of the sperm. Involved in the migration of cortical neurons and the formation of neuron leading processes during embryonic development (By similarity). Required for dopaminergic metabolism in presynaptic autoreceptors; potentially via activity as a presynaptic scaffold protein (By similarity). [Isoform ARTS]: Required for the induction of cell death mediated by TGF-beta and possibly by other apoptotic stimuli. Induces apoptosis through binding and inhibition of XIAP resulting in significant reduction in XIAP levels, leading to caspase activation and cell death. Mediates the interaction between BCL2 and XIAP, thereby positively regulating the ubiquitination and degradation of BCL2 and promoting apoptosis.
Synonyms: hCDCREL-2; C17orf47; PNUTL2; SEP4; SEPT4; hucep-7; H5; CE5B3; ARTS; MART; FLJ40121; Septin-4; BRADEION; SPGF99
Tractability: PROTAC: UniProt records ubiquitination sites on it; ubiquitination databases record sites on it.
Gene: Protein-coding gene on chromosome 17 (58,520,250 to 58,544,368, reverse strand). Ensembl gene ENSG00000108387.
Subcellular location: Cytoplasm; Cell projection, cilium, flagellum; Cytoplasmic vesicle, secretory vesicle; Cell projection, axon; Cell projection, dendrite; Perikaryon; Synapse; Mitochondrion (Isoform ARTS); Nucleus
Subcellular location (Human Protein Atlas): Annulus
Pathways (Reactome):
Programmed Cell Death: Release of apoptotic factors from the mitochondria; SMAC, XIAP-regulated apoptotic response
Gene Ontology:
Molecular function: GTP binding; GTPase activity; identical protein binding; magnesium ion binding; protein binding; molecular adaptor activity; structural molecule activity
Biological process: positive regulation of apoptotic process; positive regulation of intrinsic apoptotic signaling pathway; positive regulation of protein ubiquitination; apoptotic process; cytoskeleton-dependent cytokinesis; flagellated sperm motility; hematopoietic stem cell homeostasis; intracellular protein localization; neuron migration; regulation of apoptotic process; regulation of exocytosis; spermatid differentiation
Cellular component: dopaminergic synapse; mitochondrion; nucleus; presynapse; septin complex; sperm annulus; synapse; axon; cell division site; cytoplasm; cytosol; dendrite; microtubule cytoskeleton; mitochondrial outer membrane; perikaryon; septin ring; synaptic vesicle; motile cilium; transport vesicle
Genetic constraint (gnomAD): Loss-of-function variants: 52 observed, 108.81 expected, observed/expected ratio (o/e) 0.48, 90% interval 0.38 to 0.6. The upper end of that interval is the gene's LOEUF score, 0.6, which puts it in group 2 of 6, group 1 being the genes least tolerant of losing a copy. Missense variants: 1,046 observed, 1,303.5 expected, observed/expected ratio (o/e) 0.8, 90% interval 0.76 to 0.84. Synonymous variants: 417 observed, 493.68 expected, observed/expected ratio (o/e) 0.84, 90% interval 0.78 to 0.92.
Homologues: Orthologues: chimpanzee SEPTIN4 (98% identical), macaque SEPTIN4 (51% identical).